TM4SF1 (transmembrane 4 L six family member 1)
Synonyms: M3S1; TAAL6; L6; H-L6
Tractability: Antibody: its Gene Ontology location is reachable by antibodies, with high confidence; UniProt predicts a signal peptide or a membrane-spanning region.
Gene: Protein-coding gene on chromosome 3 (149,369,022 to 149,377,692, reverse strand). Ensembl gene ENSG00000169908.
Subcellular location: Membrane
Gene Ontology:
Molecular function: protein binding
Cellular component: plasma membrane; membrane
Genetic constraint (gnomAD): Loss-of-function variants: 19 observed, 23.42 expected, observed/expected ratio (o/e) 0.81, 90% interval 0.56 to 1.19. The upper end of that interval is the gene's LOEUF score, 1.19, which puts it in group 5 of 6, group 1 being the genes least tolerant of losing a copy. Missense variants: 251 observed, 256.52 expected, observed/expected ratio (o/e) 0.98, 90% interval 0.88 to 1.09. Synonymous variants: 107 observed, 100.12 expected, observed/expected ratio (o/e) 1.07, 90% interval 0.91 to 1.25.
Homologues: Orthologues: macaque TM4SF1 (98% identical), chimpanzee TM4SF1 (98% identical), rabbit TM4SF1 (90% identical), pig TM4SF1 (89% identical), dog TM4SF1 (85% identical), guinea pig TM4SF1 (80% identical), rat Tm4sf1 (79% identical), mouse Tm4sf1 (77% identical), tropical clawed frog tm4sf1 (72% identical). Paralogues in human: TM4SF4 (49% identical), TM4SF18 (45% identical), TM4SF5 (45% identical), TM4SF19 (31% identical), TM4SF20 (30% identical).
Diseases named in the same sentence as TM4SF1 in open-access papers:
TM4SF1 is named in the same sentence as 57 diseases in open-access papers, as found by Europe PMC text mining. Sharing a sentence is not in itself a finding about the gene and the disease. The quoted sentences say what the papers report.
breast cancer (24 papers, 2009 to 2026). A primary or metastatic malignant neoplasm involving the breast. "Tm4sf1 is highly expressed in human pancreatic cancer, breast cancer, lung cancer, and other tumors, closely linked to tumor cell growth, migration, and invasion." (PMID 38463490, 2024). "The previous studies about TM4SF1 in breast cancer progression and development were also controversial cause utilizing different cell lines randomly." (PMID 35153775, 2022). "In the MCF-7 breast cancer cell line, the overexpression of p23 results in increased invasion, which is associated with TM4SF1 downregulation." (PMID 35153775, 2022). "Two studies reported that TM4SF1 was negatively correlated with apoptosis and positively associated with tumor growth in breast cancer." (PMID 33015133, 2020). "In addition, the overexpression of p23 in the MCF-7 breast cancer cell line results in increased invasion, which is associated with TM4SF1 downregulation." (PMID 35153775, 2022). "Other studies reported that TM4SF1 expression is closely related to the metastasis and recurrence of prostate cancer, non-small cell lung cancer, and breast cancer, and that TM4SF1 expression is negatively associated with the survival of patients with squamous cell lung cancer." (PMID 27153056, 2016). "To demonstrate the interaction among TM4SF1, PKCα, and DNM2, we examined the levels of PKCα, p-PKCα, DNM2, and TM4SF1 proteins in platelets from breast cancer patients treated with a PKCα inhibitor or an anti-TM4SF1 neutralizing antibody." (PMID 39113702, 2024). "Of note, previous studies using mRNA sequencing have reported that the TM4SF1 mRNA level is also increased in platelets from patients with breast cancer." (PMID 39113702, 2024). "Among the differentially expressed genes between Tum1 and Tum2/3, Tm4sf1 is a cell membrane protein that was recently considered as a new marker of CSCs in breast cancer, lung cancer, and melanoma, and is expressed relatively higher in Tum1." (PMID 38020927, 2023). "In the present study, The Cancer Genome Atlas (TCGA) database was used to characterize TM4SF1 expression profiles between different types of breast cancer." (PMID 35153775, 2022). "The expression of TM4SF1 was first examined in breast cancer (n = 1,097) and normal breast (n = 114) TCGA data." (PMID 35153775, 2022). "The TM4SF1 mRNA expression level was downregulated in the HR+HER2- breast cancer tissue compared with that of the healthy adjacent breast tissue." (PMID 35153775, 2022). "Transmembrane 4 L six family 1 (TM4SF1) exhibits different expression patterns among the molecular subtypes of breast cancer." (PMID 35153775, 2022). "The overexpression of TM4SF1 inhibited breast cancer growth in vivo, as well as breast cancer cell viability and proliferation in vitro." (PMID 35153775, 2022). "The expression of TM4SF1 was subsequently examined in HR+HER2- patients with breast cancer by immunohistochemistry (n = 7)." (PMID 35153775, 2022). "In the present study, MCF-7 and ZR-75-1 cells (which are ER+PR+HER2- cell lines) were used to investigate the role of TM4SF1 in HR+HER2- breast cancer." (PMID 35153775, 2022). "TM4SF1 expression profiles in HR+HER2- breast cancer tissues were tested by immunohistochemistry and qRT-PCR assay; its roles in HR+HER2- breast cancer development were investigated upon TM4SF1 overexpression or knockdown." (PMID 35153775, 2022). "TM4SF1, one of the upregulated signature genes, is a known multiorgan metastasis-promoting gene, and knockdown of TM4SF1 significantly reduces brain metastasis in mouse mammary tumor cells transformed with rat erb-b2 receptor tyrosine kinase 2 (Erbb2)." (PMID 32640677, 2020). "Triple-negative breast cancer has a tendency toward higher TM4SF1 protein levels than other types of breast cancer." (PMID 33015133, 2020).
breast cancer (continued). "Several studies have reported that TM4SF1 functions as the direct target of some miRNAs (miR-141, miR-9 miR-203) to promote the self-renewal, invasion and migration of oesophageal and breast cancer cells." (PMID 33153498, 2020). "High expression of TM4SF1 predicted a poor prognosis in patients with glioma, colorectal cancer, breast cancer, papillary thyroid carcinomas and ovarian cancer but predicted good prognosis in GC, pancreatic cancer, breast cancer and MPM." (PMID 33015133, 2020). "Patients with breast cancer with higher TM4SF1 protein levels have shorter disease-free survival and overall survival time." (PMID 33015133, 2020). "TM4SF1 was also positively correlated with cell migration, played a major role in metastatic reactivation, and promoted relapse in breast cancer." (PMID 33015133, 2020). "TM4SF1 has been reported to couple with the collagen receptor tyrosine kinase DDR1 in breast cancer progression and pancreatic cancer invasion." (PMID 31142317, 2019). "Experiments on tumor cells have previously shown TM4SF1 to be important for cell growth in liver and lung cancer, motility in lung cancer, invasion in pancreatic cancer, and metastasis of breast cancer to the lungs." (PMID 31142317, 2019). "TM4SF1 has been reported to interact with discoidin domain receptor 1 (DDR1) in breast cancer and in pancreatic cancer metastasis." (PMID 31142317, 2019). "After injection of a human-mouse chimeric monoclonal antibody against TM4SF1, 22.2% (4/18) of patients with breast cancer, colon cancer, or non-small cell lung cancer produced antibodies against antibody, and these aggregated around cancer cells." (PMID 27153056, 2016). "In particular, previous research showed that cervical cancer, lung cancer, squamous cell cancer, colon cancer, and breast cancer have elevated expression of TM4SF1 mRNA, and that prostate cancer has elevated expression of TM4SF1 protein." (PMID 27153056, 2016). "Platelets promoted breast cancer metastasis, while platelets themselves could also be “educated” by proteins such as TM4SF1 derived from the tumor to alter their function." (PMID 39113702, 2024). "The expression and function of TM4SF1 in breast cancer development are unclear and may depend on the molecular subtype." (PMID 35153775, 2022). "The next experiments were designed to examine whether TM4SF1 acted as a tumor suppressor in HR+HER2- breast cancer." (PMID 35153775, 2022). "TM4SF1 mRNA was expressed at lower levels in breast cancer than in normal tissue samples." (PMID 35153775, 2022). "TM4SF1 is also highly expressed in other cancer types, including prostate, ovarian, glioma, colorectal, liver, thyroid, lung, pancreatic, and breast cancers." (PMID 35153775, 2022). "In the present study, TM4SF1 was showed to be downregulated in HR+HER2- breast cancer tissue samples, which suggested that it might act as a tumor suppressor for this breast cancer subtype." (PMID 35153775, 2022). "Notably, among the most upregulated genes we find the well-known stemness marker CXCR4, CYP1A1, which was reported to control bCSCs proliferation, development and self-renewal, and TM4SF1 that was shown to promote breast cancer stem cell traits." (PMID 34680485, 2021). "TM4SF1 is a notable family member shown to regulate cell proliferation, adhesion, and metastasis in various cancers such as lung cancer, prostate cancer, breast cancer, liver cancer, bladder cancer, and pancreatic cancer." (PMID 30897168, 2019). "Moreover, silencing of TM4SF1 suppressed breast cancer cell migration and invasion and induced apoptosis via inhibition of p-AKT/p-mTOR pathway." (PMID 30135139, 2018). "Moreover, we demonstrated that selected genes from this subset (HES1, PRKCH, ELF5 and TM4SF1) did support invasiveness in ER+ breast cancer cells." (PMID 26356672, 2015). "Thus, we investigated the plasma membrane localization of TM4SF1 in breast cancer cells." (PMID 41826695, 2026).
breast cancer (continued). "Thus, TM4SF1 suppresses the HR+HER2- breast cancer cell proliferation, but the exact role of this molecule remains unclear and deserves further investigation." (PMID 35153775, 2022). "Thus, the effect of TM4SF1 on breast cancer cell 3D organoid formation was then evaluated." (PMID 35153775, 2022). "High expression of TM4SF1 predicts a poor prognosis in many types of cancer, such as glioma, colorectal cancer, breast cancer, and ovarian cancer, but predicts a good prognosis in gastric cancer, pancreatic cancer, breast cancer, and malignant pleural mesothelioma." (PMID 35835740, 2022). "However, the expression profile of TM4SF1 in hormone receptor HR+HER2- breast cancer remains unclear." (PMID 35153775, 2022). "Prior research has demonstrated that TM4SF1 has the ability to initiate the JAK2/STAT3 signaling pathway in breast cancer, hence facilitating the spread of breast cancer to several target organs." (PMID 38762481, 2024). "TM4SF1 was once reported to be involved in tumor progression and metastasis by promoting the activation of PKCα 26; therefore, we speculated that the TM4SF1 protein derived from breast cancer cells or platelets themselves would induce PKCα activation in platelets." (PMID 39113702, 2024). "TM4SF1, as well, is known to be downregulated in hormone-positive tumours, while increased expression of MMP7 distinguishes the basal-like breast cancer subtype from other triple-negative tumours." (PMID 36536459, 2022). "Clarifying the expression profiles of TM4SF1 in HR+HER2- breast cancer and its role in this specific cancer progression is important for developing a potential therapeutic strategy for HR+HER2- breast cancer." (PMID 35153775, 2022). "Immunohistochemistry and real-time quantitative PCR assays demonstrated that the TM4SF1 protein and mRNA levels were downregulated in the HR+HER2- breast cancer tissue compared with the healthy adjacent tissue." (PMID 35153775, 2022). "A recent study revealed that TM4SF1 coupled with DDR1 was shown to promote cancer stem cell traits and metastatic reactivation and by PKCα-dependent JAK2/Stat3 signalling in breast cancer." (PMID 33153498, 2020). "Transmembrane 4 L-six family member 1 (TM4SF1) and aspartate beta-hydroxylase (ASPH), both reported as multiorgan metastasis-promoting genes in breast cancer, were included in these signature genes." (PMID 32640677, 2020). "In addition, TM4SF1 overexpression is also involved in the formation of pseudopodia in cancer cells, and this facilitates the invasion and metastasis of cancer cells, and TM4SF1 has recently been reported to stimulate breast cancer cell invasion and migration through PI3K/AKT/mTOR pathway." (PMID 27153056, 2016). "Because the TM4SF1 expression was downregulated in HR+HER2- breast cancer and the TM4SF1-overexpression inhibited MCF-7 and ZR-75-1 cell viability and proliferation in vitro, the roles of TM4SF1 in the HR+HER2- breast tumor growth were examined in a murine model." (PMID 35153775, 2022). "After quantitative calculation, the levels of serum CCL18 and CXCL1 antigens, and C1D, TM4SF1, FXR1, and ZNF573 IgG autoantibodies were significantly higher in patients with OC than in those with cervical cancer, liver cancer, breast cancer, gynecological benign tumor patients, and healthy women." (PMID 34995016, 2022). "We further downregulated the TM4SF1 expression level by siRNA transfection in MCF-7 cells and tested whether disruption of TM4SF1 in HR+/HER2-breast cancer cells affects the cell proliferation." (PMID 35153775, 2022). "Moreover, the TM4SF1 overexpression reduced the viability of MCF-7 and ZR-75-1 breast cancer cells, whilst reducing the number of colonies and 3D-organoids formed by these cell lines." (PMID 35153775, 2022). "In addition, TM4SF1 protein and mRNA levels in HR+HER2- breast cancer tissue samples were determined by immunohistochemistry and Western blot assay." (PMID 35153775, 2022).
breast cancer (continued). "In breast cancer cells, it was recently shown that the tetraspanin TM4SF1 promotes clustering of DDR1; however, in this scenario the DDR1 ectodomain was necessary for interaction with TM4SF1, while the transmembrane and cytoplasmic regions were dispensable." (PMID 28590245, 2017). "In breast cancer cells, silencing of TM4SF1 did not inhibit the kinase activation of DDR1 on cell clustering, suggesting that DDR1 had its own ability." (PMID 28368050, 2017). "In the past decade, TM4SF1 was demonstrated to be expressed and involved in the progression of different cancers, including prostate cancer (PRC), pancreatic cancer (PC), ovarian cancer (OC), breast cancer (BC), CRC, and gastric cancer (GC)." (PMID 36678607, 2023). "However, most studies indicated that the high expression of TM4SF1 is correlated with the T stage, TNM stage, and lymph node metastasis in various cancer types, including prostate, ovarian, glioma, colorectal, liver, thyroid, lung, pancreatic, and breast cancers." (PMID 35153775, 2022). "In conclusion, TM4SF1 mRNA and protein levels were downregulated in HR+HER2- breast cancer compared with noncancerous tissue samples." (PMID 35153775, 2022).
colorectal cancer (21 papers, 2018 to 2025). A primary or metastatic malignant neoplasm that affects the colon or rectum. "TM4SF1 has been recently confirmed to be associated with various tumors, including colorectal cancer, OC, lung cancer, etc. and could be a potential factor in the treatment of OC in the future." (PMID 34995016, 2022). "In colorectal cancer, TM4SF1 was found to promote cell metastasis and maintain the EMT phenotype and cancer stemness via the Wnt/β‐catenin/c‐Myc/SOX2 pathway." (PMID 38494915, 2024). "For SOX2, in colorectal cancer, it acts together with TM4SF1 to promote tumor EMT and maintain its stemness." (PMID 38164286, 2024). "Linc00707 binds to miR-206 and inhibits its negative regulation against NOTCH3 and TM4SF1, promotes the proliferation and metastasis of colorectal cancer cells." (PMID 33542193, 2021). "At the miRNA and protein levels, the expression of miRNA-206 significantly reduces the expression of transmembrane-4l-six family member-1 (tm4sf1) in promoting the proliferation and migration of colorectal cancer cells." (PMID 34503538, 2021). "TM4SF1 expression was upregulated in colorectal cancer specimens and was significantly related to advanced stage and lymph node status when compared with para-cancerous tissues." (PMID 33015133, 2020). "Several early experiences with CAR T cell therapy in colorectal cancer include phase I trials investigating targets such as transmembrane 4 L six family member 1 (TM4SF1) and epithelial cell adhesion molecule (EpCAM), which are both highly expressed in many epithelial‐derived solid tumors." (PMID 35844304, 2022). "In addition, TM4SF1 expression was higher in metastatic cancer-derived tumors than in primary tumor-derived cells from a single colorectal cancer patient." (PMID 33015133, 2020). "Additionally, prostaglandin E2 (PGE2) significantly inhibited the expression of miR-206, thus increasing the expression of TM4SF1, and its induction promoted the migration of colorectal cancer cells." (PMID 33015133, 2020). "Furthermore, TM4SF1 was a more sensitive and precise marker for the diagnosis and detection of colorectal cancer than the carcinoembryonic antigen." (PMID 33015133, 2020). "Here, we investigated whether miR-206 is involved in prostaglandin E2 (PGE2)-induced epithelial–mesenchymal transition (EMT) in colorectal cancer (CRC) cells through the targetting of transmembrane 4 L six family member 1 (TM4SF1)." (PMID 30135139, 2018). "However, the role of TM4SF1 and its potential mechanism in colorectal cancer (CRC) remain elusive." (PMID 33153498, 2020). "Employing the Wnt/β‐catenin/c‐Myc/SOX2 axis, TM4SF1 preserves the stemness and EMT of cancer cells during colorectal cancer recurrence and metastasis." (PMID 39789998, 2025). "For instance, TM4SF1 activates Wnt signaling and promotes the expression of SOX2 to maintain stem cell properties and EMT in colorectal cancer, facilitating metastasis and recurrence." (PMID 35653786, 2022). "Upregulation of miR-9 produces downregulation of TM4SF1, MMP2, MMP9 and VEGF in colorectal carcinoma, inhibiting cell migration and invasion." (PMID 32000679, 2020). "Additionally, TM4SF1 can promote cell migration, invasion, and stemness maintenance through the Wnt/β-catenin/c-Myc/SOX2 axis in various cancer, such as colorectal cancer." (PMID 37728418, 2023). "In addition, TM4SF1 was shown to increase E-cadherin expression through the AKT signaling pathway in pancreatic and colorectal cancers." (PMID 33015133, 2020).